GIPC1 (GIPC PDZ domain containing family member 1)
Diseases named in the same sentence as GIPC1 in open-access papers (continued):
Sharing a sentence is not in itself a finding about the gene and the disease.
pancreatic adenocarcinoma (3 papers, 2010 to 2014). "GIPC1 is highly expressed in human pancreatic adenocarcinoma and plays a central role the stability of IGF-1R in pancreatic adenocarcinoma cell lines." (PMID 21209904, 2010).
cervical cancer (2 papers, 2021 to 2025). A primary or metastatic malignant neoplasm involving the cervix. "In contrast, in specific contexts, such as HPV-positive cervical cancer, GIPC1 downregulation confers resistance to growth-suppressive signals." (PMID 41374987, 2025). "The downregulation of GIPC1 in cervical cancer with HPV-18 infection can lead to the resistance to cytostatic transforming growth factor β signaling through TGFβR3 destabilization." (PMID 34149809, 2021).
diabetes (2 papers, 2011 to 2016). "Additionally, we identified several genes with cASE that have been associated with diabetes (GIPC1, USP36, RNF213, KCTD12) or obesity (PIP5K1A) (78, 79, 81, –, 83)." (PMID 27709125, 2016). "For example, the inferred structurally important role of the PDZ domain-containing protein GIPC1 in diabetes is supported despite the lack of this information in the Online Mendelian Inheritance in Man database." (PMID 22034985, 2011).
epilepsy (2 papers, 2022). A brain disorder characterized by episodes of abnormally increased neuronal discharge resulting in transient episodes of sensory or motor neurological dysfunction, or psychic dysfunction. "Therefore, in this study, we aimed to explore the role of GIPC1 in epilepsy and its possible underlying mechanism." (PMID 34676980, 2022). "This proves the involvement of mGluR7 in the GIPC1‐mediated epileptogenesis mechanism and makes GIPC1 a promising therapeutic target for epilepsy." (PMID 34676980, 2022). "To date, it has been reported that there are more than 50 protein‐binding partners of GIPC1, most of which play essential roles in neuronal development, which suggests that GIPC1 may play a multifaceted role in the CNS and may also be involved in epilepsy." (PMID 34676980, 2022). "GIPC1 was downregulated in the brain tissues of patients with TLE and mice with KA‐induced epilepsy." (PMID 34676980, 2022). "In conclusion, GIPC1 is downregulated in the brain tissues of patients with TLE and mice with KA‐induced epilepsy." (PMID 34676980, 2022). "The expression patterns of GIPC1 in patients with temporal lobe epilepsy (TLE) and in mice with kainic acid (KA)‐induced epilepsy were detected." (PMID 34676980, 2022). "First, compared with that in the control group, the expression of GIPC1 decreased in the brain tissues of patients with TLE and mice with KA‐induced epilepsy." (PMID 34676980, 2022). "Thus, we explored the expression patterns of GIPC1 in the brain tissues of patients with TLE and mice with KA‐induced epilepsy and our experimental results of reduced GIPC1 also show the possible involvement of GIPC1 in epilepsy." (PMID 34676980, 2022).
glioma (2 papers, 2021 to 2022). A benign or malignant brain and spinal cord tumor that arises from glial cells (astrocytes, oligodendrocytes, ependymal cells). "Inhibition of GIPC1 decreases glioma cell proliferation and invasion and increases apoptosis in vitro." (PMID 34277411, 2021). "Indeed, Zhang’s team demonstrated that NRP1 mediates glioma progression through its interaction with the intracellular protein GIPC1 via the cytoplasmic C-terminal SEA motif." (PMID 34277411, 2021).
invasive breast carcinoma (2 papers, 2008 to 2010). A carcinoma that infiltrates the breast parenchyma. "The authors assume that GIPC-1 protein is cancer-associated and hypothesize that serum AAbs to GIPC-1 may possibly serve as a marker for invasive breast carcinoma." (PMID 21113302, 2010). "GIPC-1 staining with 27.B1 and 27.F7 antibodies was positive only in invasive breast carcinomas (27.B1 displayed a higher reactivity rate than 27.F1) whereas GIPC-1 staining with 27.B1 and 27.F7 antibodies was negative in in situ and benign tumors (P < .001)." (PMID 21113302, 2010). "Interestingly, GIPC1 staining with both 27.F7 and 27.B1 antibodies was positive in invasive breast cancer but not in in-situ carcinomas (p < 0.001)." (PMID 18721484, 2008).
melanoma (2 papers, 2010 to 2025). A malignant, usually aggressive tumor composed of atypical, neoplastic melanocytes. "Altogether, GIPC-1 expression is well preserved in control and epithelioid melanoma but significantly downregulated in RB, mixoid melanoma, and spindle melanoma, reflecting subtype-specific differences in the maintenance of epithelial adaptor proteins." (PMID 41374987, 2025). "Spindle melanoma retained more GIPC-1 than mixoid melanoma, but overall staining remained weaker than in the control." (PMID 41374987, 2025). "Taken together, these findings indicate that GIPC1 is downregulated in RB, spindle, and myxoid melanoma, while epithelioid melanoma retains control-like expression." (PMID 41374987, 2025). "GIPC1 and DAB2IP expression were preserved in epithelioid melanoma yet significantly reduced in retinoblastoma and mixoid/spindle melanomas." (PMID 41374987, 2025). "GIPC1 and DAB2IP were preserved in epithelioid melanoma and reduced in RB and mixoid or spindle melanomas." (PMID 41374987, 2025).
benign breast tumors (1 paper, 2008). "Our results clearly demonstrate elevated levels of GIPC1 in malignant, but not benign breast tumors." (PMID 18721484, 2008).
choroidal melanoma (1 paper, 2025). Malignant tumor of melanocytes of the choroid. "We examined five proteins that help cells handle nutrients and signals, Megalin, Cubilin, Caveolin-1, GIPC1, and DAB2IP, in normal eye tissue, retinoblastoma, and different forms of choroidal melanoma." (PMID 41374987, 2025).
epithelioid melanoma (1 paper, 2025). "In contrast, our study reveals that ocular tumors rarely exhibit GIPC1 overexpression, with epithelioid melanoma maintaining baseline levels rather than increasing expression." (PMID 41374987, 2025).
Hepatic steatosis (1 paper, 2026). Steatosis is a term used to denote lipid accumulation within hepatocytes. "G1 upregulates GPER1, alleviates hepatocyte steatosis and lipid deposition, modulates lipid metabolism-related proteins, ameliorates hepatic steatosis, and interacts with GAIP-interacting protein C-terminal 1 (GIPC1)." (PMID 41929249, 2026).
Infertility (1 paper, 2019). "Furthermore, gipc-1;gipc-2 and spe-15(qx529) affected spermatid activation in vitro and caused infertility due to defects in spermatids." (PMID 30990821, 2019).
Insulin resistance (1 paper, 2025). Increased resistance towards insulin, that is, diminished effectiveness of insulin in reducing blood glucose levels. "In our study, we also observed decreased salivary levels of PDZ domain-containing protein GIPC1 and Synphilin-1 in individuals with insulin resistance and T2D, which may reflect impaired lipid handling and energy homeostasis, but these findings require validation in larger studies." (PMID 41427039, 2025).
liver disease (1 paper, 2025). "By regulating PDGFR, GIPC1 promotes fibrogenesis and liver disease." (PMID 38990489, 2025).
lymph node metastases (1 paper, 2023). "GIPC1 expression levels were associated with lymph node metastasis." (PMID 38186571, 2023). "GIPC1 expression levels were also higher in patients with lymph node metastases than in those without lymph node metastases." (PMID 38186571, 2023).
ocular tumor (1 paper, 2025). "Our results differ from the high-expression profile observed in many carcinomas, as ocular tumors more commonly exhibit reduced GIPC1 expression, suggesting that GIPC1 loss may accompany dedifferentiation in RB and spindle melanoma." (PMID 41374987, 2025). "By comparison, our findings suggest that ocular tumors with GIPC1 downregulation may lack this signaling axis, possibly reducing invasive potential relative to tumors that maintain higher levels of GIPC1." (PMID 41374987, 2025). "Unlike in other cancers, where GIPC1 overexpression promotes aggressiveness, ocular tumors exhibit a distinct pattern, suggesting that GIPC1 loss may be linked to dedifferentiation but not necessarily to progression." (PMID 41374987, 2025). "Integration with public datasets highlights CAV1 and GIPC1 as adverse survival correlates in UM and positions LRP2/CUBN/DAB2IP dysregulation as features of ocular tumor biology, nominating candidate biomarkers and mechanistic targets." (PMID 41374987, 2025). "Collectively, Megalin–Cubilin endocytosis, CAV1-mediated membrane signaling, and adaptor/tumor-suppressor nodes (GIPC1, DAB2IP) define axes that may govern differentiation, metabolic supply, and invasion in ocular tumors." (PMID 41374987, 2025). "By contrast, our data in ocular tumors show predominant GIPC1 downregulation, suggesting that GIPC1-driven pro-metastatic signaling may not be a dominant mechanism in the ocular tumor microenvironment." (PMID 41374987, 2025).
oral cancer (1 paper, 2020). "Thus, the detailed mechanism by which GIPC1 mediates TGFBR3-associated inhibition of oral cancer cell migration and invasion warrants further investigation." (PMID 32471132, 2020). "Notably, in SMAD4-deficient CAL-27 oral cancer cells, only GIPC1 is essential for TGFBR3-induced suppressive activity." (PMID 32471132, 2020). "We next investigated whether ARRB2 or GIPC1 plays a role in SMAD4-independent, TGFBR3-mediated migration and invasion of oral cancer cells by knocking down ARRB2 or GIPC1 in TGFBR3-overexpressing CAL-27 cells." (PMID 32471132, 2020). "In SMAD4-positive OC-2 oral cancer cells, both ARRB2 and GIPC1 participate in TGFBR3-mediated inhibition of migration and invasion." (PMID 32471132, 2020). "In SMAD4-positive OC-2 oral cancer cells, TGFBR3-mediated suppression requires both of its cytoplasmic interacting partners ARRB2 and GIPC1." (PMID 32471132, 2020).
ovarian tumors (1 paper, 2008). "The immunohistochemical studies of 27.F7 and 27.B1 have also enabled a comparison of GIPC1 levels in different types of breast and ovarian tumors." (PMID 18721484, 2008). "Both antibodies demonstrated similar reactivity with the malignant serous carcinoma, and thus, similar ability to detect elevated levels of GIPC1 protein in this type of ovarian tumor." (PMID 18721484, 2008). "We also studied the interactions of 27.F7 and 27.B1 antibodies with human breast and ovarian tumor tissue under the working hypothesis that these two human monoclonal antibodies target different GIPC1 epitopes." (PMID 18721484, 2008).
retinoblastoma (1 paper, 2025). A malignant tumor that originates in the nuclear layer of the retina. "However, in retinoblastoma (GSE208143), LRP2 was downregulated, while CUBN, CAV1, GIPC1, and DAB2IP were upregulated." (PMID 41374987, 2025).
serous carcinoma (1 paper, 2008). "The percentage of positive cases found in benign and borderline tumors is also lower than in overtly malignant serous carcinoma, suggesting a lower incidence of enhanced GIPC1 expression in these tumor types." (PMID 18721484, 2008).
uveal melanoma (1 paper, 2025). A melanoma derived from melanocytes of the uveal tract. "Taken together, these analyses position GIPC1 as an independent prognostic biomarker and potential oncogenic driver in uveal melanoma, while DAB2IP functions as a protective tumor suppressor." (PMID 41374987, 2025). "Incorporating LRP2, CUBN, Caveolin-1, GIPC1, and DAB2IP into biomarker-driven clinical trial design could enhance risk stratification in uveal melanoma and RB and support the development of prognostic signatures that distinguish aggressive from indolent disease." (PMID 41374987, 2025). "To evaluate the prognostic relevance of LRP2, CUBN, DAB2IP, GIPC1, and CAV1 in uveal melanoma, we performed overall survival analysis using the GEPIA2 online platform." (PMID 41374987, 2025).
cancer (24 papers, 2008 to 2026). A tumor composed of atypical neoplastic, often pleomorphic cells that invade other tissues. "The GAIP-interacting protein C-terminus (GIPC1) is a regulator of autophagy and cellular trafficking and its overexpression is associated with poor survival in several cancers." (PMID 36900206, 2023). "As such, these antibodies may impact directly on GIPC1 intracellularly, and therefore may affect a variety of different cancer-associated signaling pathways." (PMID 18721484, 2008). "According to this working hypothesis, the detection of these circulating anti-cancer specific antibodies using the cancer-associated GIPC1 antigen might be a sensitive marker for certain early stage malignancies and superior to methodologies based on cancer-associated antigen detection." (PMID 18721484, 2008). "Altered GIPC1 expression has been observed in multiple cancers, where it plays a critical role in tumor initiation, progression, and metastasis 13,31-35." (PMID 41522336, 2026). "Western blotting also confirmed the reduced GIPC1 expression in tumor tissues, with higher levels in normal tissues adjacent cancer." (PMID 41522336, 2026). "GAIP-interacting protein C terminus (GIPC1) is a scaffold protein that also interacts with the NRP1 cytoplasmic region; moreover, NRP1 induces cancer cell proliferation by forming a complex that contains GIPC1." (PMID 37108554, 2023). "Since silencing GIPC1 is already an acknowledged tool in cancer research, and GIPC1 was found in the nuclei, we tested for a possible action of GIPC1 on the regulation of MACC1 gene expression." (PMID 38144523, 2023). "The roles of GIPC1 in certain cancers have been comprehensively characterized, especially in terms of transmembrane trafficking and cellular migration." (PMID 35347223, 2022). "In conclusion, this new signaling pathway of VEGF-A/NRP1 induced cancer cell proliferation by forming a GIPC1/Syx complex that activated RhoA to degrade the p27 protein." (PMID 26209534, 2015). "In summary, we proposed a novel signal transduction pathway of VEGF-A/NRP1 that induced cancer cell proliferation by forming a GIPC1/Syx complex that activated RhoA and degraded p27." (PMID 26209534, 2015). "A treatment with a cell-penetrating peptide designed to inhibit interactions between GIPC1 and Syx suppressed the activation of RhoA as well as cancer cell proliferation." (PMID 26209534, 2015). "The available expression data indicate that GIPC1 is highly expressed in every human cancer and our results suggest GIPC1 is a necessary component for human cancer growth promoted by upstream growth factors and their receptors." (PMID 21209904, 2010). "In cancer, GIPC1 was identified as an immunogenic antigen over-expressed in both breast and ovarian tumors." (PMID 21209904, 2010). "The results of these experiments reveal that these two anti-GIPC1 human monoclonal antibodies bind to cancer cells specifically but are not limited to binding a single malignant cell type." (PMID 18721484, 2008). "GIPC1 is expected to become a novel and effective anti-cancer target." (PMID 38186571, 2023). "Clinical application of combined intervention strategies targeting MACC1 expression and GIPC1 expression might contribute to restrict MACC1-induced cancer metastasis and thus to improved patient survival." (PMID 38144523, 2023). "GIPC1 has been suggested to be involved in cancer development, progression, and metastasis." (PMID 38144523, 2023). "We sought to dissect whether ARRB2 or GIPC1 plays a role in TGFBR3-dependent cancer-suppressive activity." (PMID 32471132, 2020). "GIPC1 has been suggested to play an important role in cancer cell proliferation." (PMID 26209534, 2015). "Taken together, these data indicate that GIPC1 inhibition may represent a new target for therapeutic development for the treatment of human cancers." (PMID 21209904, 2010).
cancer (continued). "We propose that GIPC1 overproduction is not a direct cause of cancer but is rather a byproduct of the cellular response to the transformed state." (PMID 18721484, 2008). "GIPC1, a PDZ-domain-containing scaffolding protein involved in the trafficking of transmembrane proteins, modulates receptor localization, internalization, and signal strength and has been implicated in cancer progression, angiogenesis, and neuronal development." (PMID 41010338, 2025). "Thus, GIPC1-targeting intervention strategies might interdict the MACC1-induced cancer metastasis formation." (PMID 38144523, 2023). "Because GIPC1 signal transduction is activated by a wide range of cell-surface receptors and because it is also known to be essential for branching morphogenesis of arterial blood vessels, targeting GIPC1 mediated pathways is a logical therapeutic strategy for the treatment of human cancers." (PMID 21209904, 2010). "Regardless of the role that GIPC1 might play in carcinogenesis, it is clearly a novel cancer-associated antigen, suggesting that further research should be conducted in order to define its role in cell transformation and cancer development." (PMID 18721484, 2008). "In conclusions, we identified a novel, dual function of GIPC1 - as protein interaction partner and as transcription factor of MACC1 – for tumor progression and cancer metastasis." (PMID 38144523, 2023). "We identified an important, dual function of GIPC1 - as protein interaction partner and as transcription factor of MACC1 – for tumor progression and cancer metastasis." (PMID 38144523, 2023). "Moreover, other genes from diverse functional groups appeared in our analysis, such as signal transducers promoting cancer growth (CD53, RAB33A, GNA11, CANX, OCRL, GIPC1, and SOS1), microtubule formation (KIF21B) and cell migration (ASAP2)." (PMID 29535628, 2018). "Within luminal A ER+ (low-grade ER+) cases and patients with ERBB2+/ER- cancers, the GIPC1 signature was not predictive of recurrence-free survival." (PMID 21209904, 2010). "This implies a difference in GIPC1 over-expression between benign and malignant tumors, independent of the tissue type." (PMID 18721484, 2008). "However, the mechanism by which GIPC1 promotes cancer growth is not well established." (PMID 21209904, 2010).